NLRP3 (NLR family pyrin domain containing 3)
Diseases named in the same sentence as NLRP3 in open-access papers (continued):
Sharing a sentence is not in itself a finding about the gene and the disease.
tumor (continued). "Supporting our findings, other studies showed an inverse correlation between the expression of ER-α and tumor secretion of the NLRP3 product IL-1β in BC tumor tissues." (PMID 36902278, 2023). "In both co-cultures, there was a significant decrease in the expression of NLRP3 inflammasome in RAW 264.7 macrophages in the background of increased levels of pro-inflammatory cytokines in the tumor microenvironments stimulated by LPS and ATP." (PMID 38018872, 2023). "Expression of inflammatory vesicles NLRP3 also induces immunosuppressive effects such as M2 macrophages to promote tumor progression." (PMID 37700835, 2023). "The innate immune-activating NLRP3-mediated inflammatory response is generally considered rather non-tumor-specific and generalized." (PMID 35741331, 2022). "Herein, we demonstrate an important role of NLRP3 inflammasome in the functional properties of MDSCs in tumor-bearing hosts." (PMID 36032139, 2022). "More recently, Kuchroo and colleagues demonstrated that inhibition of the immune checkpoint TIM-3 on migratory DCs, resulted in strong anti-tumor immunity, mediated by ROS-driven Nlrp3 inflammasome activation." (PMID 35517498, 2022). "The inflammatory context and the cell type where anti-CTLA-4/anti-PD-1-mediated NLRP3 activation takes place to instruct anti-tumor immunity remain to be determined." (PMID 36032139, 2022). "Increased expression of tumor-NLRP3 inflammasome has recently been described in various experimental models of solid tumors." (PMID 35631400, 2022). "Epstein-Barr virus latent membrane protein 1 promoted the expression of MDSC-related molecules and cytokines by activating the NLRP3 inflammasome, leading to tumor immunosuppression in nasopharyngeal carcinoma." (PMID 35739593, 2022). "The NLRP3 inflammasome is not only the central link in the occurrence of inflammation, it can also promote tumor formation, invasion, and metastasis, and has become a research hotspot in tumor treatment." (PMID 35292015, 2022). "NLRP1/NLRP3 and immune checkpoint gene correlations were verified by single-gene co-expression analyses, and tumor immune-related pathways involving NLRP1/NLRP3 were analyzed using gene set enrichment analysis (GSEA)." (PMID 36541912, 2022). "The results suggested that HPP regulates TAM polarization to improve the tumor inflammatory microenvironment, possibly through the NF-κB/NLRP3 signaling pathway." (PMID 35603205, 2022). "Both M-MDSCs and G-MDSCs from tumor-inoculated Nlrp3-/- mice lost their ability to suppress T-cell activation and proliferation and demonstrated an extensive transcriptomic reprogramming enriched in inflammatory and metabolic pathways." (PMID 36032139, 2022). "We found that tumor growth was blunted in NLRP3 null mice, which phenocopied the previously demonstrated protective effect found in caspase-1 null mice but was unaltered in AIM2 null mice." (PMID 36439171, 2022). "Our results demonstrated that extracellular ATP induces the functional activation of NLRP3 in tumor-induced MDSCs ex vivo, accompanied by IL-1β release." (PMID 36032139, 2022). "We concluded that activation of NLRP3 was driving the recruitment of immunosuppressive cell populations, which resulted in a reduction in anti-tumor immunity and ultimately led to tumor progression." (PMID 35631400, 2022). "Further, we found a much stronger enrichment of NLRP3 expression over other inflammasome pathway sensors in the tumor myeloid cells." (PMID 36439171, 2022). "We further investigated the potential mechanisms through which NLRP1/NLRP3 were involved in tumor immune-regulation by analyzing the correlations between NLRP1/NLRP3 and immune cell marker genes." (PMID 36541912, 2022). "Strikingly, systemic pharmacological inhibition of NLRP3 inflammasome significantly reduced tumor growth in tumor-bearing compared to control-treated mice." (PMID 36032139, 2022).
tumor (continued). "For example, in breast cancer, NLRP3 increases the tumor growth and metastasis by creating an inflammatory microenvironment." (PMID 35205167, 2022). "Our findings demonstrate for the first time that efferocytosis of apoptotic tumor cells activates myeloid-intrinsic NLRP3/caspase-1/IL-1β signaling in the tumor microenvironment." (PMID 36439171, 2022). "Because the roles of NLRP1/NLRP3 in immune invasion in GC are affected by various cytokines in the tumor microenvironment, further in vitro and in vivo studies are needed to elucidate the related mechanisms." (PMID 36541912, 2022). "By contrast, comparable levels of tumor burden between wild-type and Nlrp3-/- mice when treated with AOM and DSS have also been observed." (PMID 35299732, 2022). "Correspondingly, overexpression of the NLRP3 pathway correlated with inhibition of cell proliferation and induction of leukemic cells’ death, indicating NLRP3 to be a negative regulator of tumor progression in CLL." (PMID 35897704, 2022). "The expression levels of NLRP1/NLRP3 were significantly correlated with tumor stage and degree in patients with GC." (PMID 36541912, 2022). "Our previous study demonstrated the overexpression of NLRP3 in the tumor compartment compared to the non-tumor area in primary invasive BCs and its impact on disease free survival (DFS)." (PMID 35745570, 2022). "The genetic and pharmacologic inhibition of NLRP3 inhibited PMN-MDSC tumor infiltration and significantly improved the efficacy of anti-PD-1 antibody immunotherapy." (PMID 35739593, 2022). "Of note, monocytes and NLRP3 Macros displayed the highest level of MDSC gene signature, which have been reported to differentiate into tumor-associated macrophages in tumor mice models." (PMID 36741389, 2022). "The NLRP3 inflammasome alters the tumor microenvironment via secretion of pro-inflammatory cytokines IL1B (neutral in both cohorts) and IL18 (neutral in mKRAS, conserved in WT, SR = -1.144)." (PMID 36092893, 2022). "NLRP3 inhibition in addition to anti-PD-1 treatment significantly reduced tumor growth from the monotherapies (p < 0.05)." (PMID 35631400, 2022). "Taken together, these findings strongly suggest that P2X7R associated with pannexin-1 and the consequent downstream NLRP3 activation are implicated in the pathogenesis of AOM/DSS-mediated inflammation and tumor development." (PMID 35563010, 2022). "In human xenograft models of kidney cancer, IL-1β regulates tumor growth and its invasiveness, mediated by NLRP3 activation." (PMID 36376979, 2022). "NLRP3, IL-1ß and downstream IL-6 are further activated following cancer therapies including doxorubicin, tumor cell-targeting CAR T cells and immune checkpoint inhibitors, contributing to the cytokine release syndrome and cardiac toxicity." (PMID 36466820, 2022). "Several recent reports have shown that TIM-3 plays an important role in regulating dendritic cell function and inhibiting anti-tumor immunity by modulating NLRP3 inflammasome activation." (PMID 36541912, 2022). "Conclusively, these findings support an extensive transcriptomic re-programming of both M- and G-MDSCs in Nlrp3-/- tumor-inoculated animals, consistent with an inflammatory and less-suppressive phenotype." (PMID 36032139, 2022). "Activation of NLRP3 inflammasome has been shown to affect inflammatory cell death, to mediate the secretion of pro-inflammatory cytokines, and to influence anti-tumor immunity." (PMID 36387247, 2022). "NLRP3, the most documented inflammasome, is an inflammasome that exists widely in tumor cells and its expression is regulated by the NF-κB pathway." (PMID 36497244, 2022). "This is illustrated by the overexpression of NLRP3 inflammasome, which promotes aggressive tumor features, such as enhanced proliferation, survival, and metastasis." (PMID 36012769, 2022).
tumor (continued). "Since our single-cell analysis of human TME phagocytes showed a strong association of NLRP3 over other inflammasome sensors, we performed in vivo tumor growth studies in NLRP3 null mice." (PMID 36439171, 2022). "In another study, it was concluded that NLRP3 upregulation was directly correlated with epithelial to mesenchymal transition, a process that plays a key role in tumour progression." (PMID 35877745, 2022). "NLRP3 inflammasome activation plays an important role in carcinogenesis and tumour progression in these two cancer types." (PMID 36325196, 2022). "As a dominant sensor for sterile inflammatory insults, the NLRP3 inflammasome, whose activity is orchestrated by NF-κB in the tumor microenvironment (TME), plays vital roles in regulating tumorigenesis." (PMID 35740272, 2022). "NLRP3 is not only involved in the regulation of tumor itself, it also participates in the composition of the tumor microenvironment, and has dual effects of promoting and inhibiting tumorigenesis in different tissues or cell types." (PMID 36619871, 2022). "The relationships of NLRP1/NLRP3 expression and tumor-infiltrating immune cells/marker genes were assessed using the TIMER database." (PMID 36541912, 2022). "Specifically, we report a phenotypic, transcriptomic and functional re-programming between the monocytic and granulocytic subsets of MDSCs, upon Nlrp3 deletion, during tumor development." (PMID 36032139, 2022). "Cisplatin-resistant tumour cells in non-small lung cancers had downregulated NLRP3 and upon upregulation of NLRP3, tumour cells were once again sensitised to cisplatin treatment." (PMID 35806229, 2022). "Another approach under investigation is that of stimulating anti-tumor immunity by activating the NLRP3 inflammasome." (PMID 35517498, 2022). "Collectively, these results suggested that NLRP3 can act as a tumor suppressor via inhibiting the invasion and migration of HNSCC cells." (PMID 35123464, 2022). "Studies on NLRP3 also show the relation between Erβ and the inflammasome, simultaneously correlating this to tumour activity." (PMID 35877745, 2022). "The MDSC subset re-arrangement was also evident in the spleen of tumor-inoculated WT and Nlrp3-/- mice." (PMID 36032139, 2022). "LncRNA can increase the expression of NLRP3, and up-regulation of lncRNA expression can activate the NLRP3, trigger tumor pyroptosis, and lead to cell death." (PMID 35883480, 2022). "NLRP3 plays a significant role in establishing the microenvironment surrounding the PDAC tumor by modulating the expression of IL-1β." (PMID 36389791, 2022). "NLRP3 helps with tumour progression and negatively impacts a patient’s prognosis due to the production of IL-1." (PMID 35877745, 2022). "Another study found that radiotherapy can activate the AIM2/NLRP3-CasPA-IL-1 signaling pathway in mouse models, promoting tumor elimination." (PMID 35846123, 2022). "Overall, high NLRP1/NLRP3 expression levels had a more significant correlation with higher tumor grade, cancer stage and more axillary lymph nodes metastases." (PMID 36541912, 2022). "Efferocytosis of tumor apoptotic debris activates NLRP3-dependent inflammasome signaling and IL-1β production, which drives tumor progression in vivo." (PMID 36439171, 2022). "The NLRP3 inflammasomes in tumor infiltrating immune cells and stromal cells are involved in tumor progression." (PMID 35739593, 2022). "Interplay between CTSB and NLRP3 inflammasome in tumor-infiltrating MDSCs results in IL-1 β production and pro-tumor immune response." (PMID 35277559, 2022). "Next, we sought to investigate the tumor intrinsic factors that can potentially activate the NLRP3-mediated inflammasome in tumor infiltrating mononuclear phagocytes." (PMID 36439171, 2022). "We found that the expression of NLRP3 in tumour cells was significantly lower than that in normal cells." (PMID 35289335, 2022).
tumor (continued). "Following antigen presentation, the CD8+ T cells activate the NLRP3 inflammasomes in DCs, promoting IL-1β maturation and thereby contributing to anti-tumor immunity." (PMID 36376979, 2022). "In further support of the pro-tumor role of the NLRP3 inflammasome, IL-1β neutralizing antibodies were recently found to attenuate lung cancer development in a large clinical trial (CANTOS)." (PMID 35740272, 2022). "Clinical data suggest that the overactivation of NLRP3 is closely related to the enrichment of MDSCs in a variety of tumours." (PMID 35435776, 2022). "To further demonstrate that NLRP3/IL-1β signaling is a key mediator of tumor growth, we performed a rescue experiment in NLRP3 KO mice." (PMID 36439171, 2022). "In contrast, ATP released from tumor cells or perforin released from CD8+ cytotoxic T lymphocytes (CTLs) activated NLRP3 in antigen-presenting cells (APCs) and promoted immunity against tumors." (PMID 36032139, 2022). "It worth mentioning that evidence has begun to emerge about the regulatory role of the NLRP3 inflammasome in the tumor-stromal interconnection." (PMID 35804922, 2022). "The NLRP3 inflammasome is involved in tumor progression by the recruitment of myeloid cells, such as MDSC and TAM." (PMID 35739593, 2022). "We further intuitively observed NLRP3/Gasdermin D colocalization in luteolin-treated HT-29 cells and mouse tumour tissues by immunofluorescence." (PMID 36105214, 2022). "Post efferocytosis, we observed a significant increase in the transcriptional activation of Il1b and Il1r1 as well as a modest change in the mRNA levels of Nlrp3, consistent with our bulk RNA-seq analysis from sorted human tumor-derived CD11b+ cells." (PMID 36439171, 2022). "The pyroptosis-dependent canonical NLRP3 inflammasome pathway plays a dichotomous part in tumor initiation." (PMID 36376979, 2022). "The mechanisms, however, leading to NLRP3 activation in MDSCs during tumor development remain obscure." (PMID 36032139, 2022). "It is possible that in the inflammatory context of the TME, the cell type in which NLRP3 operates, the genetic background, and the tumor cell per se possess a decisive role on NLRP3 activation and function during tumor development." (PMID 36032139, 2022). "Homogeneously, our findings evidenced that NLRP1 and NLRP3 were significantly downregulated in tumor compared to normal lung tissues." (PMID 35866781, 2022). "Mechanistically, we found that phagocyte-mediated efferocytosis of dying tumor cells in the TME directly activated NLRP3-dependent inflammasome signaling to drive IL-1β secretion." (PMID 36439171, 2022). "For instance, it was recently demonstrated that, in tumor cells, NLRP3 signaling, a key player of the inflammasome pathway, can trigger HPD after anti-PD1 antibody administration." (PMID 36555441, 2022). "Herein, we reveal that targeting of the NLRP3 inflammasome in host cells, promotes tumor regression and induces re-wiring of the MDSCs, which constitute a major mechanism of tumor immune evasion." (PMID 36032139, 2022). "The possible reason was that activation of CD8+ T cells in response to PD-1 blockade induced a PD-L1/NLRP3 inflammasome signaling cascade that resulted in the recruitment of PMN-MDSC into the tumor, thus inhibited the resulting anti-tumor immune response." (PMID 35739593, 2022). "Analysis of immune infiltrates in TIMER showed that NLRP1/NLRP3 expression levels were significantly negatively correlated with tumor purity and positively correlated with multiple infiltrating immune cells in STAD." (PMID 36541912, 2022). "Among these, the expressions of 3 genes (IL6, IL1B, and NLRP3) were found to be downregulated in the tumor group while others were upregulated compared to the adjacent nontumorous group." (PMID 35069975, 2022). "Overall, these data indicate that the NLRP3 inflammasome pathway is activated and functional in MDSCs during tumor development." (PMID 36032139, 2022).
tumor (continued). "We next examined efferocytosis-induced NLRP3-dependent inflammasome activation in situ from MOC2 tumor-bearing ASC-citrine mice." (PMID 36439171, 2022). "The nude mouse tumor-bearing models were established, aimed at analyzing the influencing mechanism of the activation of miR-22-targeted NLRP3 inflammasome on activity of human cutaneous MM A375 cells." (PMID 35874899, 2022). "NLRP3/Caspase-1/IL-1β signaling axis within the tumor-infiltrating mononuclear phagocytes promotes tumor growth in GSDMD independent manner in vivo." (PMID 36439171, 2022). "The macrophage-specific deletion of glucose transporter 1 in pancreatic cancer mouse models inhibited tumor growth and NK cell infiltration by suppressing the pro-inflammatory NLRP3-IL1β axis." (PMID 35739593, 2022). "NLRP3 dysregulated activation can induce a chronic inflammatory environment that boosts tumor progression and extinguishes local immunity." (PMID 35530309, 2022). "The roles of NLRP3 inflammasome activation in carcinogenesis and tumour growth promotion in oral SCC have been well demonstrated in three modern rigorous studies carried out in one immortalised human oral epithelial cell line and several oral SCC cell lines." (PMID 36325196, 2022). "Immunohistochemistry for cleaved Caspase-1 also confirmed comparable numbers and staining intensity for cleaved Caspase-1-positive cells throughout the tumor epithelium of gp130F/F:Nlrp3-/- and gp130F/F mice." (PMID 35299732, 2022). "As described by others, we confirmed that the downstream mediator responsible for tumorigenesis was IL-1β as its depletion resulted in significant reduction of tumor growth which phenocopied both the caspase-1 and NLRP3 null mice." (PMID 36439171, 2022). "Again, the first marker to be activated in tumor tissues was NLRP3 with a cytoplasmic expression pattern in most of the tumor cells." (PMID 35532120, 2022). "Ketone body and 3-hydroxybutyric acid were confirmed to play an important role in promoting tumor immunity by inhibiting the expression of NLRP3 inflammasome." (PMID 36438725, 2022). "Knockout of NLRP3 in HCC cells also inhibited tumor growth and metastasis in vivo, as well as increased the sensitivity to NK cell cytotoxicity." (PMID 36619871, 2022). "Our findings demonstrate that efferocytosis of tumor AC creates a T cell-independent tumor permissive microenvironment by activating NLRP3 dependent inflammasome signaling and IL-1β secretion." (PMID 36439171, 2022). "The other is that NLRP3 inflammatory bodies are activated by ATP to release tumor suppressor factor IL-1β, inducing pyroptosis, thereby removing malignant tumor precursor cells and achieving the effect of anti-tumorigenesis." (PMID 36497244, 2022). "It has been found that the pyroptosis-related protein NLRP3 is highly expressed at the early stage of breast cancer, increasing immune protection and inhibiting tumor progression." (PMID 36233009, 2022). "Honglin Yan also showed that Cisplatin (DDP) had the effect of an anti-tumor on TNBC, which is brought on by up-regulating MEG3 to cause pyroptosis in NLRP3/caspase-1/GSDMD manner." (PMID 36119049, 2022). "We were able to rescue the pro-tumor effect of NLRP3 signaling with the addition of recombinant IL-1β." (PMID 36439171, 2022). "This myeloid NLRP3/IL-1β signaling axis promotion of tumor growth was found to be gasdermin D independent." (PMID 36439171, 2022). "The NLRP3 inflammasome score correlated with tumor-infiltrating lymphocytes and macrophages and was a stronger predictor for immune signatures compared with tumor mutation burden and glycolytic activity." (PMID 35739593, 2022). "While NLRP3 appears to have a predominant role in dampening anti-tumor immunity, as illustrated above, other inflammasomes have also been implicated in this process." (PMID 35517498, 2022). "Disruption of tumor-derived NLRP3, either pharmacologically or genetically, reduced STAT3 signaling in bone marrow cells." (PMID 34531850, 2021).